NIPBL (NIPBL cohesin loading factor)
Diseases named in the same sentence as NIPBL in open-access papers (continued):
Sharing a sentence is not in itself a finding about the gene and the disease.
Cornelia de Lange syndrome (continued). "The second class is Cornelia de Lange Syndrome, which can be caused with varying degrees of severity by pathogenic mutations in NIPBL (CdLS1), SMC1 (CdLS2), SMC3 (CdLS3), SCC1 (CdLS4), and HDAC8 (CdLS5)." (PMID 29263825, 2017). "NIPBL codes for a protein necessary for the cohesion of sister chromatids during mitosis and is disrupted by some translocations in Cornelia-de-Lange syndrome." (PMID 27120335, 2016). "Mutations in core cohesin subunits SMC1A, SMC3 and RAD21, or their regulators NIPBL and HDAC8, cause Cornelia de Lange syndrome (CdLS)." (PMID 26581180, 2015). "Germline mutations in the NIPBL gene with an autosomal dominant pattern and in the SMC1A gene with an X-linked pattern have been identified in Cornelia de Lange syndrome." (PMID 21707975, 2011). "Mutations in NIPBL (Nipped-B-Like) results in Cornelia de Lange syndrome (CDLS: OMIM 122470)." (PMID 19721813, 2009). "Cornelia de Lange syndrome (CdLS, OMIM # 122470, #614701, #610759, #300590, and #300882) is a rare genetic disorder caused by variants in cohesion complex genes including NIPBL (NM_133433.3), SMC1A (NM_006304.4), SMC3 (NM_005445.3), HDAC8 (NM_018486.2), and RAD21 (NM_006265.3)." (PMID 35935361, 2022). "Variants in genes encoding various structural or functional components of the cohesin complex, including RAD21, SMC1A, SMC3, BRD4, STAG1/2, NIPBL, HDAC8, WAPL, ANKRD11 and in single individuals PDS5A and ESPL1, have been implicated in Cornelia de Lange Syndrome (CdLS)." (PMID 32193685, 2020). "Because WDSTS can phenotypic overlap with Pierpont syndrome, Cornelia De Lange syndrome and Kabuki syndrome, the candidate genes causing the later three syndromes (i.e. TBL1XR1, NIPBL, SMC1A, SMC3, RAD21, HDAC8, KMT2D, and KMD6A) in our cohort have been excluded." (PMID 30305169, 2018). "Mutations in NIPBL, cohesin, and its deacetylase HDAC8 result in Cornelia de Lange syndrome." (PMID 26725122, 2016). "Furthermore, we discovered an intragenic NIPBL deletion (Cornelia de Lange syndrome, OMIM#122470) in a fetus with reduction anomaly of the upper limbs and dysmorphic features." (PMID 27846804, 2016). "Pathogenic variants in NIPBL, MAU2, SMC1A, SMC3, RAD21, and HDAC8 cause Cornelia de Lange syndrome (CdLS), a multisystem disorder characterized by intellectual disability, facial dysmorphism, growth delay, and upper limb anomalies." (PMID 41492387, 2025). "However, after conducting whole exome sequencing analysis, no genetic variants associated with Cornelia de Lange syndrome, such as NIPBL, SMC1A, SMC3, RAD21 and HDAC8 were found." (PMID 38348454, 2024). "NIPBL loads cohesin onto chromosomes, and WAPL takes it off.Haploinsufficiency for NIPBL causes a developmental disorder,Cornelia de Lange syndrome (CdLS), that is modeled byNipbl+/− mice." (PMID 36449618, 2022). "NIPBL is the gene that is most frequently (>60% of cases, OMIM 122470) found to be mutated in the human developmental disorder Cornelia de Lange syndrome (CdLS, 1 of 10,000–30,000 live births)." (PMID 29261648, 2017). "The most frequent mutations in the human developmental disorder Cornelia de Lange Syndrome (CdLS) occur in the NIPBL gene." (PMID 29261648, 2017). "Mutations in SCC2/NIPBL and genes encoding the cohesin subunits result in a developmental syndrome known as Cornelia de Lange syndrome (CdLS)." (PMID 26176819, 2015). "Heterozygous mutations in the cohesin regulator NIPBL or cohesin structural components SMC1A and SMC3 result in the multisystem developmental disorder Cornelia de Lange Syndrome (CdLS)." (PMID 19468298, 2009). "Similarly, LRS enabled the diagnosis of patients with Cornelia de Lange syndrome (CDLS) by identifying a complex chromothripsis event affecting the NIPBL gene, which had been undetectable by SRS." (PMID 39627904, 2024). "The ET domain was also shown to interact with nipped-B-like protein (NIPBL), regulating transcriptions of many genes related to a rare growth-delay disorder, Cornelia de Lange Syndrome." (PMID 37509171, 2023).
Cornelia de Lange syndrome (continued). "Indeed, previous works using different models highlighted NIPBL importance in transcriptional regulation during development and its deregulation was reported to alter the whole genome transcription and induce pathological defects, particularly in the Cornelia de Lange Syndrome (CdLS) models." (PMID 33352756, 2020). "Genetic alterations of NIPBL, SMC1A, SMC3, HDAC8, and RAD21 genes are believed to trigger the development of Cornelia de Lange syndrome." (PMID 30606125, 2019). "Additionally, B cells derived from Cornelia de Lange Syndrome patients show increased microhomology-based end joining during CSR, suggesting that cohesin, and its loading factor NIPBL, are necessary for non-homologous end joining during CSR." (PMID 25375358, 2014).
colorectal cancer (6 papers, 2013 to 2022). A primary or metastatic malignant neoplasm that affects the colon or rectum. "The somatic mutations in NIPBL have been found in gastric and colorectal cancers and have been reported to be associated with tumorigenesis by altering microsatellite instability." (PMID 36686800, 2022). "NIPBL mutation was also found in 91 gastric cancer and 100 colorectal cancer patients when using PCR-based single strand conformation polymorphism assay, indicating the correlation of NIPBL between gastric and colorectal cancer." (PMID 30713220, 2019). "Additional evidence showed that somatic mutations in the NIPBL gene were found in gastric and colorectal cancers with high microsatellite instability." (PMID 25963978, 2015). "The human genes SMC1, SMC3, NIPBL, STAG3, RNF20, FBXW7/CDC4, MRE11A, RAD54B and BLM have been found to be mutated in colorectal cancer, and together account for approximately 25% of the CIN mutational spectrum of this disease." (PMID 23382697, 2013).
non-small cell lung carcinoma (5 papers, 2015 to 2024). A group of at least three distinct histological types of lung cancer, including non-small cell squamous cell carcinoma, adenocarcinoma, and large cell carcinoma. "High expression of NIPBL is associated with poor prognosis in non-small cell lung cancer." (PMID 34335688, 2021). "NIPBL expression in detected by immunochemistry in 123 lung adenocarcinoma samples displayed a strongly positive correlation with poor prognosis of non-small cell lung cancer patients." (PMID 30713220, 2019). "More importantly, NIPBL downregulation improved chemotherapy resistance (cisplatin, paclitaxel, gemcitabine hydrochloride) of non-small cell lung cancer cells." (PMID 30713220, 2019). "Through knockdown of NIPBL protein expression, non-small cell lung cancer cell lines were used to test the potential involvement of NIPBL silencing on cell proliferation, migration, invasion, and apoptosis." (PMID 25963978, 2015). "Knockdown of NIPBL in non-small cell lung cancer cell lines significantly reduced cellular proliferation, migration, and invasion, and enhanced cellular apoptosis and sensitivity to cisplatin, paclitaxel, and gemcitabine hydrochloride." (PMID 25963978, 2015). "Survival analysis further indicated that NIPBL expression was a potential prognostic factor for non-small cell lung cancer." (PMID 25963978, 2015). "In this study, we measured the expression of NIPBL in clinical non-small cell lung cancer specimens, and determined its effects on cellular processes and chemosensitivity in vitro." (PMID 25963978, 2015). "Mechanically, NIPBL downregulation promotes autophagy and impairs DNA damage response of non-small cell lung cancer cells, indicating that NIPBL may serve as a therapeutic target of chemotherapy resistance." (PMID 30713220, 2019). "NIPBL expression conferred poor prognosis and resistance to chemotherapy in non-small cell lung cancer, suggesting that NIPBL may be a novel therapeutic target." (PMID 25963978, 2015).
acute myeloid leukemia (4 papers, 2020 to 2022). Acute myeloid leukemia (AML) is a group of neoplasms arising from precursor cells committed to the myeloid cell-line differentiation. "Since NIPBL has emerged as a potential player in myeloid cell differentiation and in the insurgence of hematological malignancies, we performed the functional enrichment analysis also using a collection of gene sets related to myeloid differentiation and acute myeloid leukemia (AML)." (PMID 33352756, 2020). "For example, somatic mutations in the eight genes that comprise the cohesin ring (SMC1A, SMC3, STAG1, STAG2, RAD21) and the cohesin-ring support genes (NIPBL, MAU2, WAPL, PDS5A, PDS5B) and CTCF are frequently found in many cancer types and are especially common in acute myeloid leukemia (AML)." (PMID 36171609, 2022).
breast carcinoma (4 papers, 2011 to 2025). "Rare NIPBL mutations were also identified in lung carcinoma, breast carcinoma, and colorectal tumors, but the pathological importance of these mutations in cancer remains unknown." (PMID 25963978, 2015). "In addition, data from the Somatic Mutation in Cancer (COSMIC) database suggested that rare NIPBL mutations were identified in lung carcinoma, breast carcinoma, and colorectal tumors." (PMID 25963978, 2015). "Importantly, we also identified potential canine-specific oncogenic drivers, such as HECTD4 in malignant and NIPBL in epithelial-derived subtypes, that have been scarcely reported in human breast cancers, underscoring the significance in veterinary contexts." (PMID 41168812, 2025). "Furthermore, in vitro studies on human breast cancer cell lines have shown that downregulation of NIPBL induces apoptosis and autophagy." (PMID 41168812, 2025). "In breast cancer cell lines, NIPBL expression increased at both mRNA and protein levels." (PMID 30713220, 2019). "Consistent with this proposition, we noted that both topoisomerase II and the RAD21 loading protein NIPBL, showed strong coordinately regulated expression with RAD21 in breast cancer cell lines." (PMID 21255398, 2011).
epilepsy (3 papers, 2013 to 2025). A brain disorder characterized by episodes of abnormally increased neuronal discharge resulting in transient episodes of sensory or motor neurological dysfunction, or psychic dysfunction. "However, in this study, it was observed that patients with NIPBL missense mutations exhibited milder phenotypes, with less frequent occurrences of intellectual developmental abnormalities and epilepsy." (PMID 40969288, 2025).
gastric cancer (3 papers, 2015 to 2025). A primary or metastatic malignant neoplasm involving the stomach. "Notably, gastric cancer patients with NIPBL mutations demonstrated significantly improved prognosis compared to those without such mutations." (PMID 40461943, 2025).
Intellectual disability (3 papers, 2012 to 2025). "AFF2, DOCK8, NIPBL, and RPS6KA3 were implicated in intellectual disability." (PMID 23227143, 2012).
Roberts syndrome (3 papers, 2014 to 2025). "Additionally, mutations in three Cohesin subunits (SMC1α, SMC3, RAD21) and in one Cohesin-interacting protein (NIPBL) have been found causal for CdLS, whereas mutations in ESCO2 are responsible for Roberts syndrome/SC Phocomelia (OMIM# 269000)." (PMID 33263776, 2021).
acute lymphoblastic leukemia (2 papers, 2022 to 2025). Leukemia with an acute onset, characterized by the presence of lymphoblasts in the bone marrow and the peripheral blood. "While this syndrome is not typically known to confer cancer predisposition, an index case of a child with simultaneous occurrence of acute lymphoblastic leukemia (ALL) and CdLS caused by a NIPBL frameshift mutation has recently been reported." (PMID 35563565, 2022).
acute megakaryoblastic leukemia (2 papers, 2021 to 2022). Acute megakaryoblastic leukemia (AMKL) is a form of acute myeloid leukemia (AML) that occurs predominantly in childhood and particularly in children with Down syndrome (DS-AMKL). "The fusion genes involving NIPBL have been reported in acute megakaryoblastic leukemia (NIPBL-HOXB9) and atypical tenosynovial giant cell tumor (NIPBL-ERG), and it is considered that the NIPBL promoter may contribute to changes in the expression of fusion partners." (PMID 36686800, 2022).
autism (2 papers, 2024 to 2025). Persistent deficits in social interaction and communication and interaction as well as a markedly restricted repertoire of activity and interest as well as repetitive patterns of behavior. "Regulatory inference using the Genie3 algorithm identified direct regulation of IGF1 by SIK1, MFRP, CHD7, NIPBL, EXOC5, and ARID2, with SIK1 and SPARCL1 significantly downregulated in autism brain organoids, potentially affecting IGF1 expression." (PMID 39376742, 2024).
developmental delay (2 papers, 2020 to 2024). "In our study, P7 who had an NIPBL missense variant had a severe phenotype with oligodactyly, severe developmental delay, and growth retardation." (PMID 33277604, 2020). "Main findings generally suggest similar developmental delays in early communicative and motor development across those with a variant in either NIPBL and SMC1A, albeit those with NIPBL variants showed greater variability in the achievement of more complex language and motor milestones." (PMID 38462617, 2024).
infantile hemangioma (2 papers, 2019 to 2021). "For example, NIPBL was identified as a direct target of miR-187-3p and NIPBL downregulation was shown to facilitate sensitivity towards treatment with propranolol in infantile hemangioma." (PMID 34707078, 2021). "Taken together, we found that miR-187-3p expression levels were down-regulated in infantile hemangioma tissues and promoted propranolol sensitivity of HemSCs via targeting NIPBL, which showed increased expression in infantile hemangioma, especially propranolol resistance patients." (PMID 30713220, 2019).
lung adenocarcinoma (2 papers, 2015 to 2019). A carcinoma that arises from the lung and is characterized by the presence of malignant glandular epithelial cells. "Here, we evaluated the expression of NIPBL in clinical samples of lung adenocarcinoma, and found that almost one-third of the samples expressed high levels of NIPBL protein, and high NIPBL expression was associated with poor clinical outcome." (PMID 25963978, 2015). "According to our immunohistochemical staining evaluation, almost one-third of the lung adenocarcinoma samples expressed high levels of NIPBL protein (39/123 cases, 31.7%)." (PMID 25963978, 2015). "Expression of NIPBL in lung adenocarcinoma ranged from weak to strong as determined by staining." (PMID 25963978, 2015).
lung carcinoma (2 papers, 2015 to 2024). "Variations in NIPBL protein and mRNA expression levels in four lung cancer cell lines H1299, A549, H661, and H1650 were quantitated by using the quantitative reverse-transcription polymerase chain reaction (qRT-PCR) and western blot analysis." (PMID 25963978, 2015). "All four lung cancer lines expressed the NIPBL protein, especially the H1299 and H1650 cell lines, in which NIPBL protein expression was high." (PMID 25963978, 2015). "Our results suggested the overexpression of NIPBL in lung cancer with proliferative potential and aberrant differentiation." (PMID 25963978, 2015). "We performed Co-IPs to determine whether NIPBL similarly interacts with KDM6B in lung cancer cells." (PMID 38378967, 2024).
Anxiety (1 paper, 2024). Intense feelings of nervousness, tension, or panic often arise in response to interpersonal stresses. "Mutations in NIPBL are the most common cause of CdLS, with 60%–70% of patients characterized by abnormal cardiac development, alongside anxiety-related behaviors and other malformations." (PMID 39585787, 2024).
atrioventricular septal defect (1 paper, 2024). "The enrichment of NIPBL mutations was detected in patients with atrioventricular septal defect, and an inadequate dose of NIPBL resulted in defective heart development in mice." (PMID 39585787, 2024).
Barrett esophagus (1 paper, 2024). Esophageal lesion lined with columnar metaplastic epithelium which is flat or villiform. "Though CdLS cells exhibit genome instability, it has been shown there is no increased risk of cancer in CdLS patients, although NIPBL variants may genetically predispose to early Barrett’s esophagus development." (PMID 39682772, 2024).
bladder cancer (1 paper, 2021). "STAG2, ESPL1 and NIPBL genes with frequent mutations in bladder cancer are involved in the sister chromatid cohesion and segregation process." (PMID 34094968, 2021). "have found that STAG2, ESPL1 and NIPBL genes with frequent mutations in bladder cancer are involved in the SCCS process." (PMID 34094968, 2021).
cardiomyopathy (1 paper, 2022). A disease of the heart muscle or myocardium proper. "Although there is evidence that pathogenic variants in NIPBL and other genes of the cohesin complex alter heart development and produce structural defects, the underlying mechanisms of the development of cardiomyopathy in individuals without congenital malformations remain unknown." (PMID 36434327, 2022).
Constipation (1 paper, 2024). Infrequent or difficult evacuation of feces. "Constipation and GERD are more common in patients with variants in the NIPBL and SMC1A genes, visual impairment in NIPBL, SMC1A, and HDAC8, structural brain abnormalities in NIPBL, and sleep problems in NIPBL and SMC1A." (PMID 38673696, 2024).
esophageal cancer (1 paper, 2023). A primary or metastatic malignant neoplasm involving the esophagus. "Therefore, miR-217-3p and miR-217-5p enhanced the radioresistance of esophageal cancer cells, and their radiation targets NIPBL and ZMPSTE24 were identified." (PMID 37569824, 2023). "The overexpression of miR-137 improved the radiosensitivity of esophageal cancer cells, and its radiation targets MAP3K20, RNF4, KDM1A, NIPBL, and NUCKS1 were identified." (PMID 37569824, 2023). "CircPRKCI knockdown inhibited the proliferation and enhanced the radiosensitivity of esophageal cancer cells by upregulating miR-186-5p, and its radiation targets YAP1, NIPBL, and NUCKS1 were identified." (PMID 37569824, 2023).
fibrosarcoma (1 paper, 2013). A malignant mesenchymal fibroblastic neoplasm affecting the soft tissue and bone. "Because NIPBL expression levels are reported to be reduced to only 60–70% of wild-type levels in CdLS, we analysed the effects on chromatin compaction of more severely reduced levels of NIPBL, achieved by siRNA knockdown in HT1080 human fibrosarcoma cells." (PMID 23760082, 2013).
gastroesophageal reflux (1 paper, 2024). "The key phenotype in the index child here is similar to the NIPBL (Nipped-B-like protein) gene associated with classic CdLS, including growth retardation and gastroesophageal reflux." (PMID 38910710, 2024).
hemangioma (1 paper, 2019). A benign vascular lesion characterized by the formation of capillary-sized or cavernous vascular channels. "In the present study, we found miR-187-3p enhances propranolol sensitivity of hemangioma stem cells via targeting NIPBL." (PMID 30713220, 2019).
KBG syndrome (1 paper, 2020). KBG syndrome is a rare condition characterized by a typical facial dysmorphism, macrodontia of the upper central incisors, skeletal (mainly costovertebral) anomalies and developmental delay. "We found that KBG syndrome was the second diagnosis for individuals harbouring causative variants in NIPBL and RAD21 genes." (PMID 32033219, 2020). "In two cases (#N19 NIPBL gene; #S36, SMC1A gene), KBG syndrome was the first suggested as most the probable clinical diagnosis." (PMID 32033219, 2020). "Whereas for NIPBL and RAD21 patients, KBG syndrome was the second most common diagnosis (top-five rank), 54.5% (18/33) and 66,7% (2/3), Rubinstein–Taybi syndrome appeared most frequently in SMC1A and HDAC8 patients, 50.0% (4/8) and 80.0% (4/5), respectively." (PMID 32033219, 2020).